FLT4 (fms related receptor tyrosine kinase 4)
Diseases named in the same sentence as FLT4 in open-access papers (continued):
Sharing a sentence is not in itself a finding about the gene and the disease.
tumor (continued). "Here, in correlation with transcriptome data, we demonstrated the detectable protein expression of KDR, FLT4, UNC5A, ADAM12, CD34, and Prox-1 in the human KS tumor microenvironment." (PMID 37046832, 2023). "Contactin 1 promotes tumor invasion and metastasis induced by VEGF-C/Flt-4/Src/p38 MAPK/C/EBPα pathway." (PMID 36518397, 2022). "Receptors for VEGF (VEGFR) are expressed on both tumor endothelium and tumor cells and VEGFs act through three different VEGF receptors VEGFR1 (Flt1), VEGFR2 (Flk 1) and VEGFR3 (Flt4)." (PMID 36291938, 2022). "According to Cancer Genome Interpreter (CGI) analysis, alterations in SETD2, BAP1, FLT4 and PTEN genes were reported as known drivers in several tumor types, and events in FGFR4 and NSD1 genes were classified as predicted drivers." (PMID 33668731, 2021). "The activities of genes in tumour vessels (such as VEGFR2 and VEGFR3 (also called FLT4)) and tumour cells can be suppressed by the multikinase inhibitor, sorafenib, and sorafenib exerts antiangiogenic and antiproliferative effects in advanced THCA." (PMID 32626543, 2020). "The VEGFR family includes VEGFR-1(Flt-1), VEGFR-2(KDR/Flk-1), VEGFR-3(Flt-4), NRP-1 and NRP-2 with VEGFR-2 is supposed to be closer to generation of tumor vessels." (PMID 29662638, 2018). "VEGFR3 (also known as Flt4), a receptor of VEGF-C, is also required for developmental or tumor angiogenesis." (PMID 26588168, 2015). "PTK787 inhibits all three VEGF receptors (VEGFR2-KDR/Flk-1; VEGFR1-FLT-1; and VEGFR3- FLT-4) and reduces the number of tumor microvessels in an animal model." (PMID 24294521, 2013). "Application of recombinant Flt-4/Fc blocked signaling of VEGF-C and also significantly decreased tumor migration and invasion." (PMID 19589137, 2009). "The best validated signalling system for tumour lymphangiogenesis involves the secreted glycoproteins VEGF-C and VEGF-D that signal via VEGF receptor-3 (VEGFR-3; also known as Flt4), expressed on the surface of lymphatic endothelial cells." (PMID 16641900, 2006). "Basic fibroblast growth factor-R1, VEGF-C, Flt-4, and ETAR were expressed in the tumour cells in the majority of cases, whereas bFGF and Flt-1 expression was rarely observed." (PMID 15841074, 2005). "Significant positive correlations were found between VEGF-C and flt-4, VEGF and KDR, VEGF and flt-1 in tumour tissues." (PMID 10487612, 1999). "To ascertain whether the immune population could be a direct target of VEGFR3/FLT4/CD310 inhibition, we first evaluated CD310 expression in tumor immune cells and in the bone marrow of mice bearing and non-bearing tumors." (PMID 41459512, 2025). "In the human PDAC patient tumor transcriptome (TCGA), we identify strong and significant correlations between tumoral GHR expression and known lymphangiogenic (LYVE1, FLT4, VEGFC, and PDPN) and angiogenic (PDGFRa, FGFR1, TGFB3, TGFB1, TGFBR2, HIF1a, IL6, and IL1B) markers." (PMID 39000545, 2024). "With regard to controlling tumor growth or metastasis, targeting the VEGF-C/Flt-4 axis may be an effective method." (PMID 38549934, 2024). "The concordant changes in protein expression results with the values detected at the gene expression can be observed in all the evaluated parameters of integrin αV, brevican, CSPG-5, versican, integrin β-5, and CD44 and only in tumor staining in the case of MDM2, MMP2, and FLT-4." (PMID 39595920, 2024). "Some candidate tumor antigens have been assessed as the best immunogenic antigens in anticancer phage-based vaccines, such as Epidermal Growth Factor Receptor (EGFR), Fms-like tyrosine kinase 4 (Flt4), and Melanoma Antigen Gene (MAGE)." (PMID 37809683, 2023). "Several genes associated with metastatic spread were upregulated in hybrid cells relative to unfused tumor cells, including activated leukocyte cell adhesion molecule (ALCAM), runt-related transcription factor 1 (RUNX1), and fms-related tyrosine kinase 4 (FLT4)." (PMID 36010865, 2022).
tumor (continued). "Ligand VEGFC (a positive regulation signaling of lymph angiogenesis) could interact with receptor FLT4 to upregulate target gene TGFB1, which is a tumor promoter in this carcinogenic progression to induce cancer cell proliferation, migration and EMT." (PMID 31126066, 2019). "Although the expression of six endothelial differentiation marker genes (PECAM1, vWF, FLT1, FLT4, KDR, CDH5) was significantly lower in normal and tumor ADSC, there was significantly greater expression of PDGFRB in ADSC when compared to BEC and NORMA1 MEC cells." (PMID 26968831, 2016). "However, recent studies have indicated that Flt-4 is also expressed in a variety of human malignancies, indicating that VEGF-C may affect cancer development and progression by direct effects on tumor cells." (PMID 20429915, 2010). "Angiogenesis-related genes (FLT1, KDR, SPARC, INSR, ANGPT2, and FLT4) and MHC-I molecules (HLA-A, HLA-B, HLA-C, HLA-E, and HLA-F) were highly expressed in cluster 3 ECs, indicating that the cells may function as antigen-presenting cells and promote tumor parenchymal angiogenesis." (PMID 37533434, 2023). "A total of 225 high-quality cells from control and 356 from tumor-draining LNs were included in the downstream analysis and their LEC identity could be confirmed by the expressions of endothelial cell markers Cd31 (Pecam1) and VE-cadherin (Cdh5) as well as lymphatic markers Prox1 and Vegfr3 (Flt4)." (PMID 35892863, 2022). "However, extensive mutational analysis of tumor genes could not identify predictive markers of regorafenib efficacy, including among genes involving in angiogenesis (FLT1, FLT2, FLT3, FLT4, KDR, TEK (TIE2), and VHL)." (PMID 33322802, 2020). "However, there are no published data on Flt-4 expression in tumour cells of DCIS yet." (PMID 15841074, 2005). "When comparing the tumor molecular profile of one of the non-responding ES patients to another patient treated previously in their clinic that did respond to pazopanib, they found that FGFR3, FGFR4 and FLT4 (VEGFR3) genes were amplified only in the responder." (PMID 36994209, 2023).
cancer (206 papers, 2001 to 2026). A tumor composed of atypical neoplastic, often pleomorphic cells that invade other tissues. "Panel targeting sequencing found that the mutation frequency of FLT4 in cancer cells of OSCC patients with OSF was extremely high, while that of patients with simple OSCC was almost non-mutated." (PMID 38050610, 2023). "In the present work, we found that the mutation frequency of FLT4 in cancer cells of OSCC patients with OSF was extremely high, while that of patients with OSCC without OSF was almost non-mutated by panel targeting sequencing." (PMID 38050610, 2023). "Our observation that FLT4 mutations are associated with carcinoma ecotypes is intriguing and future studies will examine a potential causative role for these mutations." (PMID 38067373, 2023). "Several kinase inhibitors targeting FLT4, a blood protein positively associated with the risk of HF, are approved for the treatment of cancer." (PMID 35964012, 2022). "Patient #2 possessed a germline heterozygous BRCA2 E49* mutation that underwent loss of heterozygosity in the patient’s cancer, a possibly oncogenic FLT4 E766D somatic mutation, and moderate ERBB2 amplification (5 copies) at all timepoints." (PMID 29093439, 2017). "In order to understand the connections between BIRC5, HIF1A, and FLT4 expression and specific immune cells, we conducted a correlation analysis between these oncogenes and markers of cancer-associated fibroblasts (CAFs), considering the influence of sample purity." (PMID 37509650, 2023). "Recently, CNTN1 has been reported to mediate cell functions involving multiple signaling pathways, including the Notch signaling pathway, RHOA dependent pathway, RET/PTC3 pathway, and VEGFC/FLT4 axis to promote the invasion and metastasis of cancer cells." (PMID 38562021, 2024). "We used a computational analysis and identified the BIRC5/HIF1A/FLT4 oncogenes as being highly upregulated in NSCLC and associated with cancer progression and poor prognoses." (PMID 37509650, 2023). "FLT4 is mainly expressed in the lymphatic endothelium and plays a crucial role in lymphangiogenesis and metastasis in malignant tumors." (PMID 37509650, 2023). "A few studies have reported that the expression level of FLT4 in tumors is significantly positively correlated with the development of cancer cell metastasis and poor prognosis." (PMID 38050610, 2023). "FLT4 expression was identified in various cancers; however, its involvement in NSCLC remains elusive, hence it is necessary to investigate its molecular mechanism in this disease." (PMID 37509650, 2023). "Studies had shown that the overexpression of FANCF and FLT4 resulted in proliferation, migration, and invasion of cancer cells." (PMID 34642306, 2021). "In the CHRNB4-high subgroup, CHRNB4 was co-expressed with numerous genes, such as ADCY9, NOTCH3, ARNT, NCOA1, and NCOA3, which correlated with multiple cancer-related processes, but only one gene, FLT4, was co-expressed in the CHRNB4-low subgroup." (PMID 32455963, 2020). "There were some RTK genes (EPHB6, EPHA1, EPHB3, FGFR4, PDGFRB, and FLT4) showing amplification in cancer cells." (PMID 32038722, 2019). "FLT4 gene, belonging to the vascular endothelial growth factor family, had been reported to regulate cancer cell survival and proliferation." (PMID 32038722, 2019). "COL11A1, COL6A1, MMP2, NID1, and FLT4 have been shown to have a positive role in regulating motility and invasion of various cancer cells." (PMID 28555007, 2017). "FLT4 is also known as vascular endothelial growth factor receptor 3 (VEGFR3), and it has been implicated in cancer related to its role in increasing neo-angiogenesis." (PMID 25605009, 2015). "Somatic mutations in genes within narrow MCR, including FLT4, MAPK9, SPO11 and KHDRBS2, have been reported in cancers (COSMIC v48 release)." (PMID 21151896, 2010).
cancer (continued). "In that series, VEGF-C was secreted by the intraductal carcinoma cells and was suggested to act as a growth factor for Flt-4-positive periductal blood vessels and (less evidently) for lymphatic vessels." (PMID 15841074, 2005). "EPHA2 and FLT4 have been investigated as promising targets for cancer treatment." (PMID 39818967, 2025). "Drugs targeting SIRT2 and FLT4 were mainly designed to treat cancers." (PMID 38614964, 2024). "The VEGF-C/Flt-4 axis promotes invasion and metastasis of cancer cells." (PMID 38549934, 2024). "Additionally, CNTN-1 was also reported to promote the malignant progression of cancer cells as a downstream molecule of the VEGF-C/Flt-4 axis." (PMID 35711928, 2022). "Moreover, CNTN1 was identified as a direct downstream molecule of the vascular endothelial growth factor C (VEGFC)-VEGF receptor 3 (VEFGR3)/fms-related tyrosine kinase 4 (Flt4) axis important in lymphangiogenesis and lymphatic invasion in cancers." (PMID 32752094, 2020). "The expression of FLT4 and MET markers appeared to be associated predominantly with CK (+) cells, with the abundance of CK (+) EpCAM (-) phenotype being sharply elevated in cancer stage IA samples." (PMID 32899940, 2020). "A yet larger increase demonstrated the relative median fluorescence intensity increase (ΔMFI) suggesting that not only the proportion of MET/FLT4 bearing cells increase upon cancer development, but the intensity of cells’ expression (surface density) of these markers as well." (PMID 32899940, 2020). "Next generation sequencing analysis with “Comprehensive Cancer Panel” highlighted the presence of multiple non-targetable mutations in the FLT4, UBR5, ATM, TAF1, and GUCY1A2 genes." (PMID 30172261, 2018). "Both EGFR and FLT4 have been shown to be silenced by DNA methylation in cancer." (PMID 27911866, 2017). "The mechanisms responsible for this may include activation of the p38 mitogen-activated protein kinase (MAPK) pathway by the VEGF-C/Flt-4 axis, which mediates cell migration and invasion in various cancer cells." (PMID 24119788, 2013). "Combining the mutation frequency and distribution of OSCC and OSF cancer groups, we found that the mutation frequency of FLT4 was significantly higher in OSF cancer group, while the OSCC group had no mutation of FLT4 gene, and the mutation of FLT4 gene was unique to OSF cancer group." (PMID 38050610, 2023). "The analysis of the relationship between OSCC and FLT4 gene mutation with or without OSF showed that OSCC with or without OSF was correlated with FLT4 gene mutation, and FLT4 gene mutation in OSF cancer group was significantly higher than that in OSCC group alone." (PMID 38050610, 2023). "Therefore, the development of drugs targeting the FLT4 (VEGFR3) signaling pathway may be therapeutically beneficial in cancer management." (PMID 36465863, 2022). "NGS analyses with Comprehensive Cancer Panel highlighted the presence of multiple non-targetable mutations in fms-related tyrosine kinase 4 (FLT4), ubiquitin-protein ligase E3 component N-recognin 5 (UBR5), ataxia telangiectasia mutated (ATM), and TATA-box binding protein associated factor 1 (TAF1)." (PMID 30172261, 2018). "The mutual expression of highly tumorgenic and metastatic-related genes, such as CD44, integrin α2β1, CD146, EGFR, and Flt-4, by epithelial- and mesenchymal-like cells indicates that cancer-stromal interactions of both types of cells may occur through common signaling pathways." (PMID 22330345, 2012). "Several findings have supported the role of the RTK FMS-Related Tyrosine Kinase 4, FLT4, also called VEGFR3 (Vascular Endothelial Growth Factor Receptor- 3) and its ligand, VEGFC (Vascular Endothelial Growth Factor-C), in cancer progression." (PMID 40316529, 2025). "When SIX1 is expressed in EMT cancer cells, VEGF-C is activated, and through neuropilin 2 (NRP2)/Fms-related tyrosine kinase 4 (FLT4), GLI signals in adjacent epithelial cancer cells are activated." (PMID 36624542, 2023).
cancer (continued). "Our data predict that the core matrisome elements within FGFR-wildtype ECM-High matreotype tumors can signal through integrins, FLT4, and PDGFRB on fibroblasts to induce pro-fibrogenic signaling that promotes cancer cell growth, migration, and invasion." (PMID 36404344, 2022). "Hypermethylation of CpG probes, cg00489401, cg17403609, and cg07682600 mapped to Fms-related tyrosine kinase 4 (FLT4) gene was found in 13, 12, and 11 cancers, respectively." (PMID 33801837, 2021). "Concerning additional cancer genes identified in the significantly altered regions, some were characterized as known drivers (SETD2, BAP1, FLT4 and PTEN) and others as predicted drivers (FGFR4 and NSD1), according to the CGI." (PMID 33668731, 2021). "By binding to its receptor Flt-4, VEGF-C promotes angiogenesis and/or lymphangiogenesis, thus accelerates cancer metastasis to lymph nodes and distant organs." (PMID 20429915, 2010). "VEGFR-3 (Flt-4) is primarily involved in lymphangiogenesis, with VEGF-C and VEGF-D as main ligands, which plays a crucial role in regulating lymphatic endothelial cell functions and has become a significant focus of research in cancer studies." (PMID 40006092, 2025). "Although different subgroups of ccRCC were not studied here, significant differences were found in the angiogenesis-related genes FLT1, FLT4, and KDR between cancer and benign EVs as well as ccRCC EVs and pRCC EVs, which fits more with a lower aggressive ccA phenotype." (PMID 34331598, 2021). "Additionally, many of these markers, namely, KDR, FLT4, and UNC5A, have been shown to be involved in other types of cancers, making these markers non-exclusive to KS tumorigenesis." (PMID 37046832, 2023).
infection (10 papers, 2009 to 2025). The state of being infected such as from the introduction of a foreign agent such as serum, vaccine, antigenic substance or organism. "The AMPK agonist 5-Aminoimidazole-4-carboxamide ribonucleotide (AICAR) can salvage glycolytic reprogramming and inflammasome activation in macrophages expressing mutant FLT4 to prevent recurrent infections." (PMID 38066566, 2023). "The expression of FLT4 and VEGFC is increased in macrophages after infection, and FLT4 signaling was found to be important in affecting key cellular processes, such as autophagy, inflammasome activation, and pyroptosis, all of which contribute to successful bacterial clearance." (PMID 39600882, 2024). "Upon infection, macrophages expressed FLT4/VEGFR-3 and its ligand VEGF-C, and this signaling was involved in the inhibition of CASP1 (caspase 1)-dependent inflammasome activation and pyroptosis; it also enhanced MAP1LC3/LC3 activation for bacterial elimination." (PMID 38464522, 2024). "In response to infection, toll like receptor 4 (TLR4) on macrophages recognises LPSs to induce the expression of FMS related tyrosine kinase 4 (FLT4)." (PMID 38066566, 2023). "Overall, cell culture infections corroborated observations in GI and skin KS that showed an increase in expression of STC1 and FLT4 with KSHV infection or reactivation." (PMID 37740179, 2023).
adenocarcinoma (5 papers, 2006 to 2023). A common cancer characterized by the presence of malignant glandular cells. "Interestingly, when BIRC5/HIF1A/FLT4 were upregulated in LUAD tissues, they exhibited a high presence in solid pattern-predominant adenocarcinomas, which are large and aggressive tumors with poor prognoses." (PMID 37509650, 2023).
genetic disorder (2 papers, 2014 to 2023). "MS represents a genetic disorder with the FLT4 gene playing a critical role in the development and maintenance of the lymphatic system." (PMID 40041256, 2023).
FLT4 also shares sentences with these, for which no sentence is quoted: Obesity (13 papers); bladder cancer (10); cardiac hypertrophy (8); diabetes (8); hepatocellular carcinoma (8); non-small cell lung carcinoma (8); Stroke (8); lymphatic malformation (7); colitis (6); lymphangioma (6); metabolic syndrome (6); Arthritis (5); Autoimmunity (5); esophageal cancer (5); heart failure (5); inflammatory bowel disease (5); Myocardial fibrosis (5); skin cancer (5); squamous cell carcinoma (5); aortic stenosis (4); diabetic nephropathy (4); gastric tumors (4); kidney disease (4); metastasis (4); neuroblastoma (4); osteosarcoma (4); rheumatoid arthritis (4); Sepsis (4); soft tissue sarcoma (4); 22q11.2 deletion syndrome (3).
A further 209 diseases each share a sentence with FLT4 in 3 papers or fewer.